Y_RNA (Y RNA )
Gene: Miscellaneous RNA gene on chromosome 9 (33,352,788 to 33,352,874, reverse strand). Ensembl gene ENSG00000200544.
Homologues: Orthologues: chimpanzee Y_RNA (97% identical). Paralogues in human: Y_RNA (93% identical), Y_RNA (92% identical), Y_RNA (90% identical), Y_RNA (89% identical), RNY3 (87% identical), Y_RNA (87% identical), RNY3P1 (86% identical), Y_RNA (86% identical), RNY3P14 (85% identical), Y_RNA (85% identical), RNY3P16 (84% identical), RNY3P5 (84% identical), and 88 more.